TPX2 (TPX2 microtubule nucleation factor)
Diseases named in the same sentence as TPX2 in open-access papers (continued):
Sharing a sentence is not in itself a finding about the gene and the disease.
tumor (continued). "In HCC, TPX2 overexpression indicates advanced TNM staging and poor tumor differentiation and correlates with unfavorable prognosis." (PMID 40599775, 2025). "The causal relationship between NKX6.3 depletion, cell cycle dysregulation, and the subsequent amplification of AurkA and TPX2 underscores the complex molecular pathways involved in CIN and tumor progression." (PMID 39833908, 2025). "IHC analysis demonstrated that tumour cell markers, including HMGB2, TOP2A, CENPF, and TPX2, were strongly expressed in T1, with HMGB2 showing higher expression than TOP2A." (PMID 40099956, 2025). "The discovery that CDK1, TOP2A, AURKA, TPX2, BUB1B, and CENPF are key cell-cycle regulators in NSCLC emphasizes the ongoing contribution of mitotic dysregulation to tumor growth." (PMID 41080754, 2025). "We found the increased expression of PFKP, TPX2, UBE2S, ST6GALNAC4, ADAM15, G6PD, and KPNA2, but decreased expression of GOT2 in tumor samples compared to normal samples." (PMID 40307857, 2025). "For example, TPX2 expression is elevated in HCC and its silencing inhibits the malignant behavior of tumor cells." (PMID 38833082, 2024). "Thus, therapies targeting TPX2 may revive anti-tumor immune responses." (PMID 38643462, 2024). "The results showed that TPX2, RHOV and FAM83A expression was significantly upregulated in the tumor cell lines." (PMID 39247599, 2024). "An additional link between the deregulation of the AurkA/TPX2 complex and chromosomal instability in tumours comes from studies on the phosphatase PP6, which has been demonstrated to be the AurkA T-loop phosphatase when the kinase is complexed with TPX2." (PMID 39195284, 2024). "Using the Clinical Proteomic Tumor Analysis Consortium (CPTAC) analysis, significantly elevated levels of TPX2 phosphorylation at S738 were identified in primary BRCA compared to control tissues." (PMID 38315450, 2024). "Next, using machine learning, we identified and validated three hub genes (CDC45, CDC20, TPX2), with CDC20 showing the highest correlation with tumor stemness and limited previous research." (PMID 39114311, 2024). "The results showed that, overexpression of TPX2 in MHCC97-L cells accelerated the metabolism and clearance of Sorafenib in the subcutaneous tumour tissues formed by HCC cells (the t1/2 values: 29.70 [21.38–36.75] for control group v.s." (PMID 36707511, 2023). "The low expression of miR-1294 can up-regulate the downstream target genes c-Myc, TPX2, IGF1R, and HOXA6 to promote the invasion and migration of ESCC, GM, OC, ccRCC tumor cells." (PMID 37303740, 2023). "Six of them (KIF4A, ASPM, KIF20A, KIF14, TPX2, KIF18B) are overexpressed by more than 10-fold in tumor samples and four of them (KIF11, AURKB, TPX2 and KIFC1) are essential for cell survival." (PMID 37835564, 2023). "Six of them (KIF4A, ASPM, KIF20A, KIF14, TPX2, KIF18B) warrant particular attention as they show increased expression by more than 10-fold in tumor samples compared to normal tissues." (PMID 37835564, 2023). "TPX2 depletion restricted the antitumor activity of CD8 + T cells, and TPX2 overexpression increased the antitumor effect of CD8 + T cells in tumor-bearing Cd8−/− mice." (PMID 35273149, 2022). "To determine the expression of TPX2 in different subsets of T cells, we separately isolated CD3+, CD4+, and CD8+ T cells from tumor-infiltrating lymphocytes (TILs) and peripheral blood mononuclear cells (PBMCs) from ten HCC patients." (PMID 35273149, 2022). "PARADIGM pathway features corresponding to the mitotic genes TPX2, RAE1, UBE2C, AURKA show increased activity in tumours with high NCS, consistent with the known role of chromosome segregation errors in W-CIN." (PMID 35326573, 2022). "Indepth evaluation of three genes (TTK, TPX2 and RAD54B) confirms their role in genomic instability and tumor growth." (PMID 34031527, 2021).
tumor (continued). "Among these DE-MTGs, upregulated RACGAP1, RARRES3, TPX2, MMP28, GPR87, and KIF14 with HR > 1 were regarded as oncogenes, whereas downregulated TSPAN7 with HR < 1 was regarded as a tumor suppressor." (PMID 33033514, 2020). "Consistent with the results of integrated analysis, mRNA expression of RACGAP1, RARRES3, TPX2, MMP28, GPR87, and KIF14 was significantly upregulated in PDAC tumor tissues, whereas TSPAN7 was significantly downregulated." (PMID 33033514, 2020). "The expression of TPX2 in RCC was significantly higher than that in normal renal tissue, and it was related to tumor size, histological grade, tumor stage, and poor prognosis." (PMID 32626756, 2020). "TPX2 siRNA upregulated the expression of IGFBP-3, resulting in significantly reduced CD34-positive micro vessels in the tumor." (PMID 33033514, 2020). "The IHC analysis of 66 patient samples also confirmed the overexpression of TPX2 and FOXM1 in tumor tissues." (PMID 32723329, 2020). "The expression of AURKA-B, TPX-2, MDR, Scr, and survivin by immunohistochemistry (IHC) and amplification of FGFR1 by fluorescence in situ hybridization (FISH) on tumor biopsies was also evaluated." (PMID 33202573, 2020). "In conclusion, we reported a novel signal axis through which Hh signaling regulates tumor growth via FOXM1 and TPX2." (PMID 32723329, 2020). "Further, TPX2 expression is upregulated in PDAC cell lines and tumor tissues, whereas its knockdown using siRNA suppressed the growth of PDAC cells via induction of apoptosis in vitro." (PMID 33033514, 2020). "The kinase activity of CDK5 was necessary for tumor progression, and the promoting effect of CDK5 was dependent on its substrate TPX2." (PMID 31272499, 2019). "As cell-cycle dependent proteins with interrelated functions, TOP2A, TPX2, and ASPM play key roles in the mitotic machinery that drives tumor cell replication in NSCLC and other tumor types." (PMID 31816603, 2019). "In this research, we further assessed the differential expression of five hub genes (TPX2, KIF2C, CDCA8, BUB1B, and CCNA2) in various clinical stages, and the results showed that their expression was significantly increased in advanced tumour stages." (PMID 31285741, 2019). "The survival prediction model consisting of two genes (TPX2 and MMP12) and two clinicopathological factors (tumor stage and grade) was developed." (PMID 30305064, 2018). "Age, tumor size, N stage, clinical AJCC stage, and high TPX2 expression predicted a poor prognosis in the univariate analysis (P = 0.001, 0.001, 0.000, 0.03 and 0.001, respectively)." (PMID 27777511, 2016). "Clinical analysis indicated that the positive expression of TPX2 was significantly correlated with venous infiltration, high Edmondson-Steiner grading and advanced TNM tumor stage in HCC." (PMID 25302620, 2014). "The re-expression of TPX2WT, but not TPX2K249R, facilitated the in vivo tumour growth of HepG2 xenografts with endogenous TPX2 knockdown, which was abolished by treatment with both LDHA inhibitor, GSK2837808A, and AURKA inhibitor, alisertib." (PMID 40107714, 2025). "From TCGA tumor expression data via GEPIA2, the top 100 genes positively correlated with LRFN4 expression were determined, among which TPX2 (R = 0.36), KIF18B (R = 0.39), RCE1 (R = 0.53), PCNXL3 (R = 0.49), and SAMD1 (R = 0.48) showed significant correlations (P < 0.001)." (PMID 40386777, 2025). "In addition to the cellular response to hypoxia, TPX2 positively correlated with multiple carcinogenesis-related pathways, such as the PI3K/AKT/mTOR pathway, tumor proliferation signature, and MYC targets." (PMID 38833082, 2024). "Consistently, tumour cells carrying PP6 mutations and lacking PP6 catalytic activity display increased activity (by 200%) of AurkA in the complex with TPX2." (PMID 39195284, 2024).
tumor (continued). "To further explore the role of TPX2 in advanced PDAC, we examined the tumour tissue of 139 patients from two independent study cohorts for its expression by immunohistochemistry and assessed its correlation with the patients ́ clinicopathological characteristics including outcome." (PMID 37142730, 2023). "TPX2 is upregulated in NSCLC, promoting metastasis and the progression of the tumoral disease." (PMID 36661515, 2023). "Using cross-tabulations, we did not detect associations between high TPX2 expression and gender, age group, KPS, tumour grade nor type of 1st-line chemotherapy." (PMID 37142730, 2023). "Among the top 100 genes that have similar expression patterns of KIFC1 in the tumors of the TCGA cohort, the KIFC1 expression was significantly and positively correlated with KIF2C, NCAPH, KIF4A, TPX2, and CDCA5 expression in all of the tumor types in the TCGA database." (PMID 35327439, 2022). "We found that TPX2-overexpressing CD8 + T cells significantly restricted tumor growth, and anti-PD-1 therapy synergistically inhibited tumor growth, while TPX2-depleted CD8 + T cells did not delay tumor growth and showed a poor response to anti-PD-1 therapy." (PMID 35273149, 2022). "We found that increased TPX2 nuclear expression showed a significant correlation with higher tumor grade, higher clinical stage, negative ER status, and negative PR status." (PMID 33622270, 2021). "TPX2 is the most well-connected gene within a proliferation network; its knockdown significantly affects metastasis but not tumour proliferation in oestrogen receptor-positive tumours." (PMID 32184406, 2020). "Among pathways and gene signatures differentially expressed between our tumor and adjacent normal samples (FDR q ≤ 1e-4), the CIN70 gene signature was enriched with genes positively correlated with Signature 17 activities (e.g., TPX2, NEK2, and KIF4A)." (PMID 33257699, 2020). "The protein expression of TPX2 and MMP12 was examined by immunohistochemistry in 152 tumor samples." (PMID 30305064, 2018). "Most of the validated mRNAs provided unique information about tumor aggressiveness, however, three pairs of transcripts in the validated set of 23 were correlated (P‐values < 0.05): CCNA2 and TPX2 (r2 = 0.61); SRD5A2 and DPT (r2 = 0.56); and SRD5A2 and FBLN1 (r2 = 0.73)." (PMID 28145099, 2017). "TPX2 expression was mainly observed in the nuclei of tumor cells, with no expression observed in the nuclei of cells in normal tissue." (PMID 28069036, 2017). "Among 106 samples, high TPX2 protein expression was detected in 71 samples (66.98 %), and weak or no staining was observed in 35 tumor samples (33.02 %)." (PMID 27777511, 2016). "Both SOX11 and TPX2 showed a trend of increased expression levels with increasing tumor grade, whereas BCL11A did not." (PMID 23506684, 2013). "Screening tumor samples for AURKA, TPX2, and MYBL2 expression is feasible, and could be incorporated into design of clinical trials for Kinesin-5i response." (PMID 19259408, 2008). "Interestingly, no mouse models for TPX2 overexpression are reported, while TPX2-haploinsufficient mice display chromosomal imbalances and a shorter tumour-free lifespan, with increased probability to develop spontaneous tumours." (PMID 39195284, 2024). "Low expression of miR-1294 can up-regulate the expression of downstream protein-coding genes microtubule nucleation factor (TPX2), IGF1R, MYC proto-oncogene, bHLH transcription factor (c-Myc) and TRL4, TRL6, TRL8, TRL9, enolase 1 (ENO1), thereby promoting the proliferation of various tumor cells." (PMID 37303740, 2023). "The role of TPX2 in tumor metabolism and tumor immunity has not yet been discovered." (PMID 36304254, 2022).
tumor (continued). "The expression of TPX2 in tumor tissues is higher than that in non-tumor tissues." (PMID 34539726, 2021). "Furthermore, TPX2, ZWINT, UBE2C, CCNB2, CDK1, BUB1, and BIRC5 may orchestrate the stemness, proliferation, and invasion of tumor cells." (PMID 34671679, 2021). "Together, our results demonstrate the strong correlation between TPX2 expression and both molecular and clinical metrics of aggressive disease and poor clinical outcome, while also arguing that TPX2 IHC is not an appropriate standalone assay for the determination of CIN in human tumor samples." (PMID 33622270, 2021). "However, in the remaining 3 paired tissues, the levels of TPX2 expression were similar, even lower, in tumor tissues than in non-tumor tissues (No. 7, 12 and 15)." (PMID 27777511, 2016). "Furthermore, the relationship between TPX2 and angiogenesis, which is a key regulatory mechanism of tumor progression, has never been investigated." (PMID 25914189, 2015). "To more directly assess whether tumor cell proliferation was indeed not affected by knockdown of Tpx2 in our model system we quantified proliferating cells in the metastatic lesions and primary tumors of 6DT1 shTpx2 and 6DT1 shCtrl-injected mice." (PMID 25368990, 2014).
infection (5 papers, 2012 to 2025). The state of being infected such as from the introduction of a foreign agent such as serum, vaccine, antigenic substance or organism. "Our results revealed the differential expression of the genes encoding aurora kinases A (Aurka) and B (Aurkb) together with the Aurka-interacting/regulatory proteins, Aunip, Hmmr, and Tpx2 in response to sublethal PVM infection." (PMID 34959580, 2021). "In contrast, the expression of ROS-related genes (HPX2, HPX7, HPX8A, HPX8B, HPX8C, MnSOD1 and TPX2) was inhibited in the Ae. aegypti midgut 1 day after infection with Plasmodium gallinaceum, whereas DBLOX, DUOX1, TPX3 and TPX2 levels were induced." (PMID 30986216, 2019). "In TPx-2 KO1-2-infected mice, gametocytes were also observed from 2 days after infection but peaked 5 days after infection." (PMID 23146411, 2012).
digestive system cancer (3 papers, 2020 to 2023). A primary or metastatic malignant neoplasm involving any part of the digestive system. "The expression of TPX2 is related to the TNM stage and pathological grade of various digestive system cancers, with increased expression having been shown to be significantly associated with poorer prognosis." (PMID 33033514, 2020).
TPX2 also shares sentences with these, for which no sentence is quoted: glioblastoma (4 papers); medullary thyroid carcinoma (3); astrocytoma (2); hepatitis B (2); viral infection (2); acute myeloid leukemia (1); adenocarcinoma (1); bacterial infection (1); benign breast tumors (1); bladder urothelial carcinoma (1); brain glioma (1); capillary leak syndrome (1); carcinoma in situ (1); carcinosarcoma (1); cervical squamous cell carcinoma (1); chordoma (1); colorectal adenocarcinoma (1); Ductal Carcinoma (1); esophageal tumor (1); frontotemporal dementia (1); giant-cell tumor of the bone (1); gynecological cancer (1); gynecological tumors (1); head and neck cancer (1); hereditary disease (1); infectious disease (1); invasive ductal carcinoma (1); kidney cancer (1); leiomyoma (1); Lobular Carcinoma (1).
A further 19 diseases each share a sentence with TPX2 in 1 paper.